Y_RNA (Y RNA )
Gene: Miscellaneous RNA gene on chromosome 17 (62,036,833 to 62,036,945, forward strand). Ensembl gene ENSG00000200842.
Homologues: Orthologues: chimpanzee Y_RNA (100% identical). Paralogues in human: Y_RNA (86% identical), Y_RNA (85% identical), RNY1 (84% identical), Y_RNA (84% identical), Y_RNA (83% identical), RNY1P11 (82% identical), Y_RNA (82% identical), Y_RNA (81% identical), RNY1P10 (81% identical), RNY1P8 (81% identical), RNY1P7 (80% identical), Y_RNA (80% identical), and 97 more.